HTATIP2 (HIV-1 Tat interactive protein 2)
Description:
Represses translation by preventing reactivation of elongation factor eEF1A (By similarity). May also inhibit nuclear import by competing with nuclear import substrates for binding to a subset of nuclear transport receptors. Has additionally been proposed to act as a redox sensor involved in cellular oxidative stress surveillance.
Synonyms: CC3; TIP30; FLJ26963; SDR44U1
Tractability: Small molecule: a structure with a bound ligand is known; it has a high-quality binding pocket. PROTAC: ubiquitination databases record sites on it; its protein half-life has been measured.
Gene: Protein-coding gene on chromosome 11 (20,355,910 to 20,383,782, forward strand). Ensembl gene ENSG00000109854.
Subcellular location: Cytoplasm
Subcellular location (Human Protein Atlas): Cytosol
Gene Ontology:
Molecular function: protein binding; protein serine/threonine kinase activity; catalytic activity
Biological process: positive regulation of programmed cell death; positive regulation of transcription by RNA polymerase II; protein autophosphorylation
Cellular component: cytoplasm; cytosol; mitochondrion
Genetic constraint (gnomAD): Loss-of-function variants: 24 observed, 21.25 expected, observed/expected ratio (o/e) 1.13, 90% interval 0.82 to 1.59. The upper end of that interval is the gene's LOEUF score, 1.59, which puts it in group 6 of 6, group 1 being the genes least tolerant of losing a copy. Missense variants: 255 observed, 277.24 expected, observed/expected ratio (o/e) 0.92, 90% interval 0.83 to 1.02. Synonymous variants: 95 observed, 112.65 expected, observed/expected ratio (o/e) 0.84, 90% interval 0.71 to 1.
Homologues: Orthologues: chimpanzee HTATIP2 (99% identical), pig HTATIP2 (92% identical), rabbit HTATIP2 (91% identical), dog HTATIP2 (90% identical), guinea pig HTATIP2 (89% identical), mouse Htatip2 (88% identical), rat Htatip2 (86% identical), tropical clawed frog htatip2 (66% identical), zebrafish htatip2 (63% identical), Caenorhabditis elegans C33F10.14 (36% identical).
Diseases named in the same sentence as HTATIP2 in open-access papers:
HTATIP2 is named in the same sentence as 55 diseases in open-access papers, as found by Europe PMC text mining. Sharing a sentence is not in itself a finding about the gene and the disease. The quoted sentences say what the papers report.
hepatocellular carcinoma (14 papers, 2013 to 2025). A malignant tumor that arises from hepatocytes. "Downregulation of HTATIP2/TIP30 has also been observed in other cancer types, including melanoma, colon cancer, breast cancer, neuroblastoma, and hepatocellular carcinoma." (PMID 23800048, 2013). "HTATIP2 knockout mice are prone to spontaneous hepatocellular carcinoma and other tumors." (PMID 36817429, 2023). "It has been shown that HTATIP2/TIP30 levels are decreased in variant-small cell lung carcinoma (V-SCLC), classic-SCLC, neuroblastoma (NB), colon cancer, melanoma, prostate cancer, and hepatocellular carcinoma (HCC)." (PMID 34688245, 2021). "Our previous studies have demonstrated that sorafenib can promote the dissemination of hepatocellular carcinoma (HCC) through downregulation of HTATIP2, a suppressor of tumor growth and metastasis that is associated with inhibition of angiogenesis." (PMID 25008315, 2014). "HPA analysis of protein expression showed that PRDX6, GCLM, HTATIP2, NOL10, KIF18A, RAP2A and GDI2 were highly expressed in the hepatocellular carcinoma tissues compared with normal control tissues." (PMID 34760691, 2021). "HTATIP2 is a tumor suppressor gene in malignancies such as non-small cell lung cancer and hepatocellular carcinoma because, when active, it induces apoptosis, limits metabolic adaption of cancers glucose limitation, and inhibits metastasis." (PMID 36817429, 2023).
breast cancer (11 papers, 2013 to 2025). A primary or metastatic malignant neoplasm involving the breast. "This inhibitory role may facilitate Htatip2 as a tumor repressor since down-regulation of Htatip2 is associated with development of a number of cancer and/or induction of aggressive metastasis, including lung cancer, hepatocarcinoma, breast cancer, brain tumor." (PMID 30777014, 2019). "HTATIP2 (also known as TIP30 or CC3) was first identified as a metastasis suppressor in breast cancer and was often found to be downregulated in various cancers." (PMID 27977763, 2016). "HTATIP2 frequently exhibits downregulation in various tumor cells, such as breast cancer, colon cancer, pancreatic cancer, melanoma, glioblastoma, neuroblastoma, SCLC, and HCC cells." (PMID 25008315, 2014). "Similarly, Htatip2 (Tip30), a tumor suppressor in various cancers, was downregulated in Erbb2 breast cancer, but upregulated in DEN-induced liver cancer following Srsf3 knockout." (PMID 40568073, 2025). "Several cell culture studies have demonstrated the role of HTATIP2/TIP30 in a number of tumor cell lines, including neuroblastoma, breast cancer, glioblastoma, and melanoma." (PMID 23800048, 2013).
pancreatic cancer (5 papers, 2014 to 2020). "HTATIP2 is involved in apoptosis function in liver metastasis related genes, gastric cancer and pancreatic cancer." (PMID 33133160, 2020).
glioblastoma (3 papers, 2013 to 2023). The most malignant astrocytic tumor (WHO grade IV). "The DNA methylome of glioblastoma revealed recurrent epigenetic silencing of HTATIP2, which encodes a negative regulator of importin β‐mediated cytoplasmic–nuclear protein translocation." (PMID 37491696, 2023). "Here, we aimed at elucidating the impact of epigenetic silencing of HTATIP2 on the biology of glioblastoma, mediated by potential aberrant regulation of subcellular localization of cancer‐relevant proteins." (PMID 37491696, 2023). "Aberrant promoter methylation of HIV‐1 TAT‐interactive protein 2 (HTATIP2) attenuates the negative regulatory capacity of glioblastoma cells to reduce nuclear translocation of cancer‐relevant proteins such as the base excision repair enzyme N‐methylpurine DNA glycosylase (MPG)." (PMID 37491696, 2023). "Epigenetic silencing of HTATIP2 may thus increase nuclear localization of MPG, thereby enhancing the capacity of the glioblastoma cells to repair treatment‐related lesions and contributing to treatment resistance." (PMID 37491696, 2023).
glioma (3 papers, 2016 to 2025). A benign or malignant brain and spinal cord tumor that arises from glial cells (astrocytes, oligodendrocytes, ependymal cells). "This downregulation of HTATIP2 is reportedly associated with promoter CpG island methylation in HCC, CRC, esophageal squamous cell carcinoma and glioma." (PMID 27977763, 2016). "Notably, according to a study by Dong and colleagues, HTATIP2 downregulation results from promoter methylation and predicts poor clinical outcomes in gliomas." (PMID 41146049, 2025).
cardiac hypertrophy (2 papers, 2019 to 2025). "Here, we characterized the 30 kDa protein TIP30 (also termed Htatip2) as inhibitor of mRNA translation and cardiac hypertrophy and revealed that it protects against heart failure during pathological stimulation." (PMID 31468715, 2019).
diabetes (2 papers, 2022 to 2023). "While our study adds new insights into the role of HTATIP2, further work using a fully in-vivo mouse model could help unveil the molecular mechanisms by which HTATIP2 contributes to the pathogenesis of diabetes and autoimmunity." (PMID 36817429, 2023). "Except for the completely restored DEGs, Sal treatment mitigated the expression of approximately 73.08% up-regulated DEGs and 66.35% down-regulated DEGs induced by diabetes, including 8 oxidation-related genes (Aldh4a1, Acad12, Ado, Kdm4d, Acacb, Mical1, Th and Htatip2)." (PMID 35370972, 2022).
liver cancer (2 papers, 2021 to 2025). An epithelial or non-epithelial malignant neoplasm that arises from the liver. "Another study reported that interventional treatment of primary liver cancer can reduce serum HTATIP2/TIP30 and B7-H4 levels, improve liver function and quality of life and prolong the survival times of patients." (PMID 34760691, 2021).
ovarian carcinoma (2 papers, 2013 to 2022). A malignant neoplasm originating from the surface ovarian epithelium. "In this study, we demonstrated for the first time a potential role of HTATIP2/TIP30 in ovarian cancer which will enlighten future studies targeting HTATIP2/TIP30 in ovarian cancer treatment, diagnosis, and prevention." (PMID 23800048, 2013). "This protein has been found to be associated with some gynecological cancers; as such, this study aimed to investigate blood HTATIP2/TIP30 levels in patients with ovarian cancer." (PMID 23800048, 2013). "In the present study, we found that HTATIP2/TIP30 levels were elevated in the serum samples of patients with ovarian cancer." (PMID 23800048, 2013). "Future clinical and experimental studies are required to determine the conclusive role of HTATIP2/TIP30 in ovarian cancer." (PMID 23800048, 2013). "For the following genes, we found no significant changes in expression in fibroblasts after treatment with exosomes from ovarian cancer cells: HTATIP2 (HIV-1 Tat interactive protein 2, 30 kDa), IL1B, TGFB1 and TNFSF10 (TRAIL, Tumor necrosis factor (ligand) superfamily, member 10)." (PMID 36012171, 2022). "At the clinical level, our study is unable to suggest whether HTATIP2/TIP30 expression is suppressed or enhanced at the onset of ovarian cancers, when it is confined to the ovaries." (PMID 23800048, 2013). "HTATIP2/TIP30 also interacts with an estrogen receptor α-interacting coactivator and regulates ERα-mediated c-Myc transcription, suggesting that it has a role in ovarian cancer." (PMID 23800048, 2013). "In light of these data, we can suggest that the increase in HTATIP2/TIP30 levels in ovarian cancer may be related to its intrinsic protein kinase activity." (PMID 23800048, 2013). "All of these studies support our findings that HTATIP2/TIP30 has a potential role in ovarian cancer, and that HER2/neu expression may be related to increased HTATIP2/TIP30 levels." (PMID 23800048, 2013). "All of this information led us to hypothesize a potential role of HTATIP2/TIP30 in ovarian cancer." (PMID 23800048, 2013). "We demonstrated the potential role of HTATIP2/TIP30 in ovarian cancer for the first time, thereby enlightening future studies targeting HTATIP2/TIP30 in ovarian cancer treatment, diagnosis, and prevention." (PMID 23800048, 2013).
serous ovarian cancer (2 papers, 2013 to 2014). "Similarly ARID3B overexpressing cells exhibited increased expression of genes (ST3GAL6, ADAM19, and HTATIP2) reported to be part of the serous ovarian cancer ascites CSC signature." (PMID 25327563, 2014). "The aim of our study was to investigate the levels of HTATIP2/TIP30 in serous ovarian cancers, using the enzyme-linked immunosorbent assay (ELISA) method, and to determine whether altered HTATIP2/TIP30 levels correlate with cancer occurrence." (PMID 23800048, 2013).
ankylosing spondylitis (1 paper, 2021). An autoimmune chronic inflammatory disorder characterized by inflammation in the vertebral joints of the spine and sacroiliac joints. "The authors found that serum HTATIP2/TIP30 levels in patients with ankylosing spondylitis were higher than in healthy controls." (PMID 34688245, 2021).
Autoimmunity (1 paper, 2023). The occurrence of an immune reaction against the organism's own cells or tissues. "This gene network shows that HTATIP2 expression could enhance β cell autoimmunity by facilitating the infiltration of immune cells into the pancreas from the surrounding microvasculature and migration of these cells into the islets." (PMID 36817429, 2023).
contact dermatitis (1 paper, 2021). An inflammatory skin condition caused by direct contact between the skin and either an irritating substance or an allergen. "This study aimed to explore the potential role of HTATIP2/TIP30 in contact dermatitis (CD), which is one of the most common inflammatory cutaneous conditions." (PMID 34688245, 2021). "In this study, we aimed to investigate serum HTATIP2/TIP30 levels in patients with contact dermatitis, a prototypical cutaneous inflammatory condition." (PMID 34688245, 2021). "Third, it is hard to draw a robust conclusion on the relationship between HTATIP2/TIP30 and contact dermatitis, since tissue expression of HTATIP2/TIP30 and detailed immunological evaluations were not made." (PMID 34688245, 2021).
COVID-19 (1 paper, 2023). A disease caused by infection with severe acute respiratory syndrome coronavirus 2. "In addition, we found other cell-death-associated proteins (CD274, HTATIP2, and S100A8) in the patients, which supports the observation that severely diseased COVID-19 patients develop thrombocytopenia." (PMID 37681923, 2023).
myeloma (1 paper, 2025). "We selected genes (PHOX2A, CDH2, and HTATIP2) whose methylation levels significantly changed to validate their expression via qRT‒PCR in CD138+ myeloma cells." (PMID 41146049, 2025).
osteosarcoma (1 paper, 2018). A usually aggressive malignant bone-forming mesenchymal neoplasm, predominantly affecting adolescents and young adults. "HTATIP2 is involved in the control of cell apoptosis, growth, metastasis, angiogenesis and DNA repair; it has been found to be expressed in different tumors, but it has never been described in osteosarcoma." (PMID 30093974, 2018).
type 1 diabetes (1 paper, 2023). "This study implicates HTATIP2 as a new type 1 diabetes gene acting via T cell regulation." (PMID 36817429, 2023).
tumor (33 papers, 2010 to 2025). "The literature shows that it is believed that the mechanism of HTATIP2/TIP30’s anti-metastatic properties is that it inhibits angiogenic properties of tumor cells and predisposes tumor cells to apoptosis." (PMID 23800048, 2013). "Increased expression of HTATIP2 is associated with decreased expression of Ang-1 in tumor cells." (PMID 37847559, 2023). "HTATIP2 is an oxidoreductase required for tumor suppression and may act as a redox sensor linked to transcription through regulation of nuclear import." (PMID 35484098, 2022). "The increased sensitivity of LUAD to EMT processes activated by drug therapy and the enhancement of tumor metabolic plasticity, regulation of tumor adaptation to hypoxia, and promotion of an aggressive tumor phenotype are consequences of the deficiency in HTATIP2 expression." (PMID 37965333, 2023). "Since downregulation of HTATIP2 has been associated with acquired sorafenib resistance, a cytotoxicity study was carried out to examine the impact of HTATIP2 knockdown on tumor cell response to sorafenib treatment in vitro under normoxic and hypoxic conditions." (PMID 32545251, 2020). "HTATIP2 was originally described as a tumor suppressor, and HIV1-binding protein with intrinsic serine/threonine kinase activity." (PMID 38247867, 2024). "Reduced Htatip2 expression increases tumor vascularization in mice, while forcing the expression of HTATIP2 in tumor cell lines inhibits their ability to promote EC proliferation and migration." (PMID 37847559, 2023). "The evidence gathered from literature highlighting the potential antiangiogenic role of HTATIP2 expression in tumor biology fits mechanistically with our data." (PMID 37847559, 2023). "HTATIP2 promoter methylation has also been reported from other tumor types and found most commonly in GBM and low‐grade glioma, with 70 to over 80% prevalence, according to a pan‐cancer analysis." (PMID 37491696, 2023). "Overexpression of Htatip2 in tumor cell lines has previously been shown to diminish expression of Angpt1 mRNA." (PMID 37847559, 2023). "All the gene signatures other than those of PRDX6 and HTATIP2 were correlated with tumour purity and B cell, CD4+ T cell, CD8+ T cell, macrophage, neutrophil and dendritic cell levels." (PMID 34760691, 2021). "Additional recent studies reported that metformin enhanced the anti-tumor effect of sorafenib or regorafenib by reducing HIF2α expression and increasing HTATIP2 expression at the protein level." (PMID 32545251, 2020). "Taken together, the data suggest that the absence of HTATIP2 expression results in tumor metabolic rewiring that aggravates the aggressive tumor growth." (PMID 32545251, 2020). "A recent study showed that HTATIP2 expression was decreased significantly in tumor cells derived from the Hep2 laryngeal squamous cell carcinoma (LSCC) xenograft tumors that were carried by BALB/c nude mice treated with cisplatin once a week for 5 weeks." (PMID 32545251, 2020). "In another previous study, we found that sorafenib directly downregulated HTATIP2 in tumor cells and provoked liver micrometastases." (PMID 25008315, 2014). "In contrast to MVD, high HTATIP2 expression in HCC was an independent protective prognostic factor after curative resection and was associated with small tumor size, a lower rate of intrahepatic metastasis and microvascular invasion, and much better prognosis." (PMID 25008315, 2014). "Here, we also described a negative correlation between HTATIP2 expression and MVD, implying that the putative antiangiogenic property plays a crucial role in the tumor inhibitory effects of HTATIP2." (PMID 25008315, 2014). "In the present study, we found that tumor MVD was negatively correlated with the expression of HTATIP2." (PMID 25008315, 2014). "In a previous study we found that low-dose sorafenib promoted invasiveness and metastatic potential of HCC with higher expression of HTATIP2, although it inhibited primary tumor growth." (PMID 23741443, 2013).